SLC25A1 (solute carrier family 25 member 1)
Description:
Mitochondrial electroneutral antiporter that exports citrate from the mitochondria into the cytosol in exchange for malate. Also able to mediate the exchange of citrate for isocitrate, phosphoenolpyruvate, cis-aconitate and to a lesser extent trans-aconitate, maleate and succinate. Substrate exchange across the membrane occurs consecutively with one substrate being transported first, then dissociating from the substrate binding site before the second substrate binds for transport in the opposite direction. In the cytoplasm, citrate plays important roles in fatty acid and sterol synthesis, regulation of glycolysis, protein acetylation, and other physiopathological processes.
Synonyms: CTP; CIC; SLC20A3; CMS23; D2L2AD; SEA
Tractability: Antibody: UniProt predicts a signal peptide or a membrane-spanning region. PROTAC: ubiquitination databases record sites on it; its protein half-life has been measured.
Gene: Protein-coding gene on chromosome 22 (19,175,575 to 19,178,788, reverse strand). Ensembl gene ENSG00000100075.
Subcellular location: Mitochondrion inner membrane
Pathways (Reactome):
Transport of small molecules: Organic anion transport by SLC5/17/25 transporters
Gene Ontology:
Molecular function: citrate secondary active transmembrane transporter activity; citrate:succinate antiporter activity; tricarboxylic acid transmembrane transporter activity; citrate transmembrane transporter activity
Biological process: mitochondrial citrate transmembrane transport; negative regulation of ferroptosis; transmembrane transport; succinate transmembrane transport
Cellular component: extracellular exosome; mitochondrial membrane; mitochondrion; nucleus; mitochondrial inner membrane
Genetic constraint (gnomAD): Loss-of-function variants: 26 observed, 34.88 expected, observed/expected ratio (o/e) 0.75, 90% interval 0.55 to 1.03. The synonymous counts are far from expectation, so gnomAD's model fits this gene poorly and the ratio says little. Missense variants: 370 observed, 383.49 expected, observed/expected ratio (o/e) 0.96, 90% interval 0.88 to 1.05. Synonymous variants: 204 observed, 162.35 expected, observed/expected ratio (o/e) 1.26, 90% interval 1.12 to 1.41.
Gene-disease validity (ClinGen):
ClinGen rates the evidence that SLC25A1 causes each of these diseases.
mitochondrial disease (autosomal recessive): Definitive.
Homologues: Orthologues: chimpanzee SLC25A1 (99% identical), macaque SLC25A1 (99% identical), dog SLC25A1 (97% identical), guinea pig SLC25A1 (96% identical), rat Slc25a1 (95% identical), mouse Slc25a1 (94% identical), pig SLC25A1 (92% identical), tropical clawed frog slc25a1 (86% identical), zebrafish slc25a1b (83% identical), zebrafish SLC25A1 (67% identical), rabbit SLC25A1 (66% identical). Paralogues in human: UCP2 (29% identical), SLC25A18 (28% identical), UCP3 (28% identical), SLC25A12 (27% identical), SLC25A22 (27% identical), SLC25A21 (27% identical), SLC25A13 (26% identical), SLC25A47 (25% identical), SLC25A48 (25% identical), SLC25A38 (24% identical), UCP1 (24% identical), SLC25A20 (24% identical), and 37 more.
Diseases named in the same sentence as SLC25A1 in open-access papers:
SLC25A1 is named in the same sentence as 84 diseases in open-access papers, as found by Europe PMC text mining. Sharing a sentence is not in itself a finding about the gene and the disease. The quoted sentences say what the papers report.
lung carcinoma (13 papers, 2018 to 2025). "Overexpression of mitochondrial citrate carrier (SLC25A1) was proved to be associated with reduced survival of lung cancer patients." (PMID 32802843, 2020). "Our in silico analysis revealed that SLC25A1 overexpression was associated with significantly reduced overall survival and median survival in lung cancer patients." (PMID 29888201, 2018). "Interestingly, high SLC25A1 expression in lung cancer patients has already been linked with poorer overall survival compared to lung cancer patients with low SLC25A1 expression in an earlier report." (PMID 29888201, 2018). "Importantly, high expression of SLC25A1 in lung cancer patients was associated with a poor outcome, particularly after successful surgery (R0-resection), pointing to a potential clinical relevance of SLC25A1 particularly in terms of tumor recurrence." (PMID 29888201, 2018). "Moreover, in silico analysis of publically available databases applying the Kaplan–Meier plotter tool (kmplot.com) revealed that overexpression of SLC25A1 was associated with reduced survival of lung cancer patients suggesting a potential link to aggressive cancers." (PMID 29888201, 2018). "To evaluate the role of SLC25A1 as a ferroptosis inhibitor, we silenced its expression in A375 and A549 lung cancer cells and observed increased sensitivity to ferroptosis triggered by RSL3, erastin, and cystine deprivation." (PMID 39881208, 2025). "Oxidative stress stimulation induces the enhanced expression of SLC25A1, whereas treatment with the inhibitor 1,2,3-benzene-tricarboxylic acid reveals dysregulated mitochondrial redox regulation in lung cancer cells." (PMID 40722961, 2025). "SLC25A1 is involved in the oxidative stress defense system for survival in glioblastoma; prostate cancer; and lung cancer cells, such as NCI-H460 and A549." (PMID 40722961, 2025). "Earlier literatures showed that high expression of SLC25A1 was correlated with shorter survival time in lung cancer and colorectal cancer patients." (PMID 37981593, 2023). "Similar to our findings in Kaplan–Meier Plotter and TCGA database, SLC25A1 played a detrimental role in breast cancer, lung cancer (adenocarcinoma), and skin cancer (melanoma)." (PMID 37981593, 2023). "Genetic and pharmacologic inhibition of SLC25A1 (SLC25A1i) increased D-2-HG-levels and sensitized lung cancer and glioblastoma cells to the cytotoxic action of ionizing radiation (IR)." (PMID 35869047, 2022). "We found that SLC25A1 is overexpressed in most lung cancers relative to normal tissues and in metastatic sites." (PMID 29651165, 2018). "We split the lung cancer patient cohort by median of SLC25A1 expression into “High” and “Low,” respectively." (PMID 29888201, 2018). "Exposure to acute or chronic cycling severe hypoxia/reoxygenation stress triggered upregulated expression of SLC25A1 in lung cancer, prostate cancer, and glioblastoma cells in vitro." (PMID 29888201, 2018). "Our findings strongly suggest that SLC25A1 plays a role for maintenance of the antioxidant defense of lung cancer cells with tolerance to acute or chronic cycling severe hypoxia with potential impact on the sensitivity of the cells to ROS-induced damage." (PMID 29888201, 2018). "But here we demonstrate for the first time that SLC25A1 has a role in lung cancer cell radiation resistance." (PMID 29888201, 2018). "Moreover, the SLC25A1 inhibition enhanced the sensitivity to cisplatin in ovarian carcinoma cells and increased the radiosensitivity of hypoxic lung cancer cells." (PMID 37981593, 2023). "Moreover, analysis of publicly available datasets revealed that lung cancer patients with high SLC25A1 expression had a poorer prognosis." (PMID 35869047, 2022). "Additionally, SLC25A1 also dramatically accelerated the in vivo growth of h1299 cells (lung cancer cell line) in xenograft models, while inhibition of SLC25A1 reduced the growth of lung cancer." (PMID 34839347, 2021).
lung carcinoma (continued). "Multiple evidences show that SLC25A1 overexpression is associated with poor prognosis of lung cancer and estrogen receptor-negative breast cancer." (PMID 32265986, 2020). "High levels of SLC25A1 expression are associated with poor prognosis in lung cancer and estrogen receptor negative breast cancer." (PMID 32265986, 2020). "However, our primary goal was to evaluate the use of SLC25A1 as a therapeutic target to overcome radioresistance in chronically Hx lung cancer cells." (PMID 29888201, 2018). "Of note, SLC25A1 displayed a higher expression in lung cancer patients compared to normal lung tissue suggesting that SLC25A1 might be a relevant target in lung cancer." (PMID 29888201, 2018). "To gain insight into a potential relevance of SLC25A1 for tolerance of lung cancer cells to chronic cycling severe hypoxia, we used our established cell model of so-called “anoxia-tolerant” NCI-H460 lung cancer cells and the respective control cells termed “oxic” NCI-H460 cells." (PMID 29888201, 2018). "Moreover, another study in lung cancer also reported that inhibition of SLC25A1 could increase the sensitivity of ionizing radiation (IR) in NCI-H460 cells." (PMID 34839347, 2021). "High expression of SLC25A1 or ACLY has been reported in multiple cancers including colorectal, breast, and lung cancer." (PMID 39881208, 2025). "Pharmacological inhibition of SLC25A1 by 1,2,3-benzene-tricarboxylic acid (BTA) treatment enhanced radiosensitivity of lung cancer cells and delayed repair of radiation-induced DNA damage." (PMID 35869047, 2022). "(ii) Pharmacologic inhibition of SLC25A1 by BTA reduced cellular antioxidant capacity, enhanced the generation of mitochondrial ROS and abrogated the increase in radioresistance of lung cancer cells induced by adaptation to chronic cycling severe hypoxia." (PMID 29888201, 2018). "However, here we expand these findings with respect to the importance of SLC25A1 in terms of recurrence and progression of lung cancer suggesting that SLC25A1 may be an attractive therapeutic target for tumor cell-specific radiosensitization at least in patients with high SLC25A1 expression." (PMID 29888201, 2018). "Similarly to SLC25A1, ACLY is significantly elevated in a variety of cancers, including melanoma, hepatocellular carcinoma, lung cancer, prostate cancer, and breast cancer." (PMID 39881208, 2025). "More recently, α-KG has been identified as a radiosensitizer for lung cancer treatment in combination with CTPI-2, an inhibitor of mitochondrial citrate carrier (SLC25A1; CIC), whereas α-KG alone had no pharmacological effects." (PMID 41306524, 2025). "It has been shown earlier that inhibition of SLC25A1 by BTA reduces the growth of xenograft tumors of breast, bladder or lung cancer cells without any evidence for additional normal tissue toxicity." (PMID 29888201, 2018).
breast carcinoma (8 papers, 2021 to 2025). "In agreement with our observations in CRC, it was also reported that knockdown of SLC25A1 in breast cancer by shRNA transfection remarkably blunted cell proliferation and colony formation in MBA-MD-231 cells." (PMID 34839347, 2021).
22q11.2 deletion syndrome (6 papers, 2012 to 2025). 22q11.2 deletion syndrome (DS) is a chromosomal anomaly which causes a congenital malformation disorder whose common features include cardiac defects, palatal anomalies, facial dysmorphism, developmental delay and immune deficiency. "Heterozygous SLC25A1 gene deletions are associated with congenital 22q11.2 microdeletion syndromes, namely Velo-Cardio-Facial and DiGeorge syndromes." (PMID 33499062, 2021). "In addition, SLC25A1 is part of the chromosomal interval deleted in 22q11.2 deletion syndrome, a microdeletion syndrome associated with neurodevelopmental, psychiatric, and neurodegenerative diseases." (PMID 37171075, 2023). "Moreover, SLC25A1 is part of the chromosomal interval deleted in 22q11.2 deletion syndrome, which is associated with increased risk for myriad neurodevelopmental disorders, most prominently schizophrenia." (PMID 34312306, 2021). "In addition, few patients manifested combined D-2- and L-2-hydroxyglutaric aciduria and diGeorge syndrome caused by a SLC25A1 mutation on one allele and a microdeletion of 22q11.2, which contains SLC25A1 and two other genes, on the homologous chromosome." (PMID 32340404, 2020). "SLC25A1 has been implicated as a hub factor underlying a mitochondrial protein network, which includes SLC25A4, that is disrupted in 22q11.2 deletion syndrome cells." (PMID 37171075, 2023). "Recent work suggests that SLC25A1 and SLC25A4 are hub genes in the network of the perturbed brain proteome associated with 22q11.2 deletion syndrome." (PMID 34312306, 2021). "The mitochondrial citrate transporter gene, SLC25A1 or CIC, maps on chromosome 22q11.21, a region amplified in some tumors and deleted in developmental disorders known as velo-cardio-facial- and DiGeorge syndromes." (PMID 23100451, 2012).
prostate carcinoma (6 papers, 2018 to 2025). A carcinoma that arises from epithelial cells of the prostate gland. "Our discovery of significant interactions between SLC39A1 and genes related to citrate metabolism, notably SLC25A1, suggests potential new therapeutic targets for further investigation in the context of prostate cancer and other SLC39A1-related disorders." (PMID 40355755, 2025). "Previous studies reported that SLC25A1 expression was enhanced in lung and prostate cancer cell lines under conditions of acute or chronic cycling hypoxia/re-oxygenation stress." (PMID 37981593, 2023). "Thus, treating prostate cancer cells in a hypoxic TME with the SLC25A1 inhibitor, 1,2,3-benzene-tricarboxylic acid (BTA) could not only yield direct tumor-specific killing, but it could also potentiate the activity of concomitant radiation or chemotherapy interventions." (PMID 32103057, 2020).
steatosis (6 papers, 2020 to 2024). Increased lipid within the cytoplasm of cells. "Inhibition of Slc25a1 has been linked to decreased steatosis, protection against steatohepatitis, and reduced adipose tissue inflammation." (PMID 38533910, 2024). "Similar to our findings in CRC, a previous study in inflammatory steatohepatitis (NASH) also showed that suppression of SLC25A1 with CTPI-2 (a specific inhibitor of SLC25A1) reverted steatosis, glucose intolerance, and inflammation in the liver tissue." (PMID 34839347, 2021). "Inhibition of CiC/SLC25A1 with a specific inhibitor compound CTPI-2 (2-((4-chloro-3-nitrophenyl)sulfonamido)benzoic acid) reverses steatosis, glucose intolerance, and inflammation in HFD-fed mice." (PMID 32947972, 2020). "Particularly interesting is the observation that heterozygous mice with undetectable levels of Slc25a1 protein in both liver and WAT were almost completely protected from steatosis." (PMID 31959914, 2020). "The liver-specific deletion of Slc25a1 (Alb-Cre; Slc25a1lox/lox) leads to attenuation of HFD-induced steatosis." (PMID 32947972, 2020).
congenital myasthenic syndrome (5 papers, 2019 to 2025). Congenital myasthenic syndrome (CMS) is a group of genetic disorders of impaired neuromuscular transmission at the motor endplate characterized by fatigable muscle weakness. "We complemented SLC25A1 knockdown by ectopically expressing either wild-type or a transport-dead p.R282H CiC mutant identified in human patients with congenital myasthenic syndromes." (PMID 39854459, 2025).
Obesity (5 papers, 2020 to 2026). Accumulation of substantial excess body fat. "Here the authors report that adipocyte-specific deficiency of IL-1 Receptor-Associated Kinase M (IRAKM) ameliorates diet induced obesity, potentially via the mitochondrial citrate carrier Slc25a1 and reduced de novo lipogenesis." (PMID 35585086, 2022). "The findings here suggest that specifically disrupt interactions of IRAKM with Slc25a1 or specific IRAKM inhibitors might offer potential therapeutic strategies for the treatment of obesity-associated pathologies." (PMID 35585086, 2022). "Consistently, previous proteomics analyses of SAT adipocytes of individuals with obesity and insulin resistance revealed a reduced abundance of SLC25A1." (PMID 41077621, 2026). "Citrate produced in the citric acid cycle can be exported from mitochondria to cytosol via the transporter SLC25A1, which was decreased in individuals with severe obesity in the present study." (PMID 41077621, 2026). "Genes of interest include the mitochondrial citrate transporter Slc25a1, as well as genes known to regulate hematopoiesis (Cd44), anaerobic glycolysis (Ldha), and obesity/lipolysis (Plin1)." (PMID 32293246, 2020). "Obesity-prone SR mice, when contrasted against the HFD controls, showed a unique upregulation of the citrate transport protein (Slc25a1, 2.8-fold) responsible for the export of citrate in exchange for malate from cytosol." (PMID 38276304, 2024).
ovarian carcinoma (5 papers, 2020 to 2025). A malignant neoplasm originating from the surface ovarian epithelium. "In ovarian cancer patients, SLC25A1 mRNA levels are also associated with resistance to platinum-based chemotherapy, and blocking CTP function enhances sensitivity of cultured ovarian carcinoma cells to platinum." (PMID 32265986, 2020). "Consistent with this, over-activation of SLC25A1 has been observed in ovarian cancer, and its inhibition improved cancer cell sensitivity to platinum-based chemotherapy." (PMID 37876796, 2023). "Moreover, other genes related to the neuromuscular junction like the MuSK activator Agrin, Membralin and SLC25A1 are expressed in SKOV3WT ovarian carcinoma cells and overexpressed in SKOV3 cells exposed to cisplatin." (PMID 39592661, 2024).
colorectal cancer (4 papers, 2021 to 2024). A primary or metastatic malignant neoplasm that affects the colon or rectum. "SLC25A1 is highly expressed in breast, lung, and colorectal cancer, where its expression is closely associated with advanced clinicopathological features and poor prognosis." (PMID 37981593, 2023). "Reports have indicated that downregulation of SLC25A1 expression can significantly inhibit the proliferation of colorectal cancer cells by suppressing the progression of the G1/S cell cycle phase and inducing apoptosis, as observed in both intact‐cell and lysate‐based PISA." (PMID 39350574, 2024). "Here, our observation of CTPI2-induced apoptosis and cell death was in good accordance with the recent discovery in colorectal cancer, which indicated that knockdown of SLC25A1 significantly inhibited colorectal tumor growth by inducing apoptosis both in vitro and in vivo." (PMID 35869047, 2022). "We wanted to question whether SLC25A1 overexpression contributes to the pathogenesis and aberrant lipid metabolism in colorectal cancer (CRC)." (PMID 34839347, 2021).
Glucose intolerance (4 papers, 2020 to 2023). Glucose intolerance (GI) can be defined as dysglycemia that comprises both prediabetes and diabetes. "Moreover, truncated OxPAPC down-regulated the expression of Cav1 (caveolin 1), which has been shown to increase hepatic lipid droplet size in NAFLD, and up-regulated Slc25a1, which has recently been associated with hepatic steatosis and glucose intolerance by dysregulation of hepatocyte metabolism." (PMID 35857497, 2022).